POLE (DNA polymerase epsilon, catalytic subunit)
Diseases named in the same sentence as POLE in open-access papers (continued):
Sharing a sentence is not in itself a finding about the gene and the disease.
endometrial cancer (continued). "To explore whether the favorable clinical outcomes of patients with POLE mutations are associated with diminished malignantlly, we examined chemoresistance, cell cycle transition, and cell migration and invasion of endometrial cancer cells in term of POLE mutations." (PMID 36313640, 2022). "However, less frequent POLE variants that might also contribute to the pathogenesis of endometrial cancer remain largely unknown." (PMID 36313640, 2022). "Although the mutations in the POLE gene could be analyzed in 74 patients who had adequate tumor samples, stratification of these 81 endometrial cancer patients into 4 groups by POLE mutation, MSI status, and copy number cluster based on TCGA’s classification still could not be achieved." (PMID 34439385, 2021). "Interestingly, in a Japanese cohort of concurrent ovarian and endometrial cancer, the frequency of POLE mutations was high (five of 8 cases; 62%) detected by Sanger sequencing; however, the reported POLE mutations (Q292E, E396V, D287N, and N293D) do not correspond to known hotspot mutations." (PMID 34158040, 2021). "Previous studies demonstrated that POLE mutants are associated with improved clinical outcomes in various types of malignancy that were explained by enhanced host immune responses and increased sensitivity to anticancer drugs in colorectal and endometrial cancers." (PMID 32433714, 2020). "However, how do POLE mutations affect the prognosis of endometrial cancer?" (PMID 31864301, 2019). "However, the potential relationship and underlying mechanism between POLE mutations and the prognosis of endometrial cancer patients remains unclear." (PMID 31864301, 2019). "POLE-mutated and MSI-H subtype endometrial cancer are immune-infiltrated tumors, whereas the copy-number high subtype is immune-suppressive tumor and the copy-number low subtype is immune-desert tumor." (PMID 41705240, 2026). "The increasing recognition of POLE as a biomarker has led to calls for routine testing of endometrial cancers." (PMID 40072110, 2025). "POLE-mutated and MSI endometrial cancers are associated with high neo-antigen loads and abundant TILs, accompanied by overexpression of PD-1/PD-L1, making them ideal candidates for PD-1 targeted immunotherapy." (PMID 40264788, 2025). "Specifically, miR-20b-5p was up-regulated in endometrial cancer relative to normal endometrium but relatively down-regulated within the POLE+ subset." (PMID 41226475, 2025). "This methodology involves the gene sequencing of POLE and the use of immunohistochemical surrogates analogous to the known genomic subcategories of endometrial cancer established by the TCGA." (PMID 39796739, 2025). "In endometrial cancer, high tumor mutational burden (TMB) due to MSI-H or POLE mutations presents an opportunity to enhance immune surveillance through bsAbs targeting immune checkpoints or acting as T-cell engagers." (PMID 41211166, 2025).
endometrial cancer (continued). "The Cancer Genome Atlas (TCGA) proposed a molecular classification system dividing endometrial cancers into four subtypes: POLE-ultramutated, microsatellite instability-high (MSI-H), copy-number low (CN-low), and copy-number high (CN-high)." (PMID 40978043, 2025). "Polymerase Proofreading-Associated Polyposis (PPAP) or POLE-mutated and Microsatellite Instability (MSI) endometrial cancers have high tumor-infiltrating lymphocytes and neoantigens." (PMID 40352591, 2025). "The germline POLE/POLD1 genetic testing should be considered in the context of a strong family history of colorectal or endometrial cancer (two or more relatives) or a single relative with colorectal cancer or endometrial cancer <60 years." (PMID 40936703, 2025). "PPAP is caused by heterozygous germline POLE or POLD1 PV and is associated with gastrointestinal polyposis, as well as adult-onset colorectal and endometrial cancer, and other tumor types." (PMID 39031223, 2024). "Within this dataset of tumors harboring POLE mutations (n = 447/14,541), low TMB (TMB-L, <10 mut/Mb) was observed in 39.1% of colorectal cancers (36/92), 30.9% of endometrial cancers (95/307), and 50.0% of ovarian cancers (24/48)." (PMID 38282550, 2024). "This cohort study explores the prevalence of and outcomes associated with POLE and POLD1 alterations among patients of different races with endometrial cancer (EC)." (PMID 38231514, 2024). "Similar to POLE-mutated cancers, MSI-high endometrial cancers often respond well to immunotherapy, particularly checkpoint inhibitors, due to the high mutational load." (PMID 38539507, 2024). "Therefore, activating the cGAS-STING pathway through POLE mutations may help improve the survival of patients with endometrial cancer, and the stimulation of intrinsic immunity in cancer cells by POLE mutations provides a theoretical basis for personalized treatment of malignant tumors." (PMID 39445027, 2024). "In summary, the POLE subgroup was more likely to occur in early-stage endometrial cancer and in some patients with favorable prognostic pathologic features." (PMID 39839791, 2024). "In endometrial cancer, TCG>TTG substitutions comprised 17.3% of POLE variants, and TCT>TAT comprised 4.8% of variant POLE variants." (PMID 38282550, 2024). "What is the prevalence of POLE and POLD1 pathogenic alterations and their association with outcomes in patients of different racial groups with endometrial cancer (EC)?" (PMID 38231514, 2024). "Among the MSS TMB-H subset of Group 4 tumors, POLE variants associated with TMB-H were observed in colorectal cancer and endometrial cancer (n = 14); most variants were missense (8/14), but nonsense and other alterations were also observed (6/14)." (PMID 38282550, 2024). "Among the four TCGA subgroups of endometrial cancer, the POLE subgroup is the least common and is also seen to be the least represented in our statistics." (PMID 39839791, 2024). "In one study report, two cases of recurrent POLE ultra-mutated and MSH6 hyper-mutated endometrial carcinoma refractory to conventional surgical and chemotherapeutic treatments were effectively treated with the anti-PD-1 monoclonal antibody Nivolumab." (PMID 38893147, 2024). "The study highlighted that POLE mutations are primarily found in young male patients with CRC and young female patients with endometrial carcinoma, often indicating a favorable prognosis." (PMID 39273605, 2024). "Herein, we presented a novel somatic mutation in POLE exonuclease domain associated with ultra-mutational signature and MMR deficiency in endometrial cancer." (PMID 36765365, 2023). "In 2013, based on the genomic characteristics of endometrial cancer, The Cancer Genome Atlas identified 4 distinct subgroups: POLE ultramutated, microsatellite instability hypermutated, copy number-low, and copy number-high." (PMID 37058063, 2023).
endometrial cancer (continued). "In recent years, the TCGA has outlined four molecular subtypes of endometrial cancer including POLE ultramutated, microsatellite instability hypermutated, copy number low, and copy number high." (PMID 37568665, 2023). "Especially, DNA replication fidelity disruption and DNA repair defects result in high TMB in POLE mutations and MSI endometrial cancer, respectively." (PMID 37109350, 2023). "POLE-mutated and MSI-H endometrial cancers are linked to a high abundance of tumor-infiltrating lymphocytes and neoantigen loads, implying a more effective outcome with immunotherapy." (PMID 36936912, 2023). "The mutations of S297F and V411L of POLE were reported to be hotspot mutations and associated with high TMB in endometrial carcinoma, which was present exclusively in the high-risk group in our study." (PMID 36936374, 2023). "In this study, by targeted sequencing of POLE in tumor tissue samples from 138 patients with endometrial cancer, we identified four POLE hotspot EDMs P286R, V411L, R375Q, and P452L, among which R375Q and P452L were reported for the first time." (PMID 36313640, 2022). "Defining subtypes of endometrial cancer (microsatellite instability, high-copy number, low-copy number, and mutant POLE types) in The Cancer Genome Atlas (TCGA) demonstrated clinical utility." (PMID 36536419, 2022). "Functionally, the hotspot EDMs promote chemoresistance, cell cycle arrest, and metastatic abilities of endometrial cancer cells in vitro, suggesting that POLE affects a wider range of cellular processes beyond DNA replication and proofreading." (PMID 36313640, 2022). "We observed that POLE-P286R, R375Q, and P452L induced cisplatin chemoresistance in endometrial cancer cells." (PMID 36313640, 2022). "Specifically, they found that subgroups with high mutational load (POLE-mutated types and those with high microsatellite instability (MSI-high)) were less common in uterine carcinosarcomas than in other endometrial cancers." (PMID 36139624, 2022). "Recently, whole‐genome sequencing or targeted POLE sequencing has been widely used to identify new POLE EDMs involved in endometrial cancer." (PMID 36313640, 2022). "HEC-1A and AN3CA cells that exhibited dramatically weaker POLE protein expression than other endometrial cancer cell lines were selected for the following experiments." (PMID 36313640, 2022). "In this study, we performed targeted POLE sequencing in the tumor tissue samples of these three types of endometrial cancer and found that 32/138 (23.2%) of patients carried POLE EDMs." (PMID 36313640, 2022). "TCGA and subsequent studies showed that POLE-mutant endometrial cancers typically present as high-grade or poorly differentiated tumors." (PMID 34439385, 2021). "In the TCGA cohort, POLE-mutant endometrial cancers were typically high-grade or poorly differentiated." (PMID 34439385, 2021).
endometrial cancer (continued). "Previous studies have classified endometrial cancer into four subtypes: POLE, MSI-H, copy-number low and copy-number high subtypes." (PMID 33879792, 2021). "Compared with POLE, POLD1 mutations are less frequently observed in endometrial cancers, although a few POLD1 mutations have been reported in G3 EC." (PMID 35002543, 2021). "Further research showed that POLEmut endometrial cancer patients had a 10-year recurrence free survival of 100% in comparison to the POLE wild type group which had a recurrence free survival of 80.1%." (PMID 33546293, 2021). "Lastly, data on the molecular categorization of the various types of endometrial carcinoma and EC2 (POLE-ultramutated, microsatellite instability mutated, copy number high, and copy number low) are not available in population-based cancer registries." (PMID 34354948, 2021). "We collected 553 primary endometrial cancer specimens and performed Sanger sequencing for exons 9, 13, and 14 of POLE (exonuclease proofreading domain)." (PMID 32457342, 2020). "Recent years, the Cancer Genome Atlas (TCGA) molecular subgroups of endometrial cancer, including POLE, MSI, copy-number-high, and copy-number-low, showed a good potential prognostic value of endometrial cancer (EC)." (PMID 33585205, 2020). "Three primary tumors—one MMR-deficient ovarian cancer, one MMR-deficient endometrial cancer and one MMR-proficient CRC—from two carriers of POLE p.Met294Arg, were analyzed." (PMID 32792570, 2020). "Considering the genetic heterogeneity of endometrial cancer and the co-occurrence of p190A and POLE mutations in endometrial cancer, we analyzed the YAP status in p190A-WT/POLE-MUT or p190A-MUT/POLE-MUT endometrial cancer specimens." (PMID 32457342, 2020). "More studies are necessary to investigate the mutant POLE in endometrial cancer therapy and how mutant POLE can be applied to benefit patients." (PMID 31864301, 2019). "And previous study suggested germline mutations affecting the exonuclease domain of POLE predispose to CRC and endometrial cancer." (PMID 30886832, 2019). "On the other hand, the expression of AMF/PGI has also been detected in POLE mutant and wild type endometrial cancer patients." (PMID 31864301, 2019). "In POLE mutants and wild type endometrial cancer patients, the expression pattern of AMFR/gp78 was similar as that of AMF/PGI (FC = 1.26, P = 0.00002)." (PMID 31864301, 2019). "In our results, we found that POLE expression was increased in endometrial cancer patients (FC = 1.65, P = 8.1e-15)." (PMID 31864301, 2019). "In view of this association, we concluded that this ovarian POLE CS of OV594 likely originates from the endometria and shares ancestry with the synchronous endometrial carcinoma." (PMID 31672974, 2019). "Expert histopathological review of 51 POLE‐mutant endometrial cancers revealed four with a concomitant and spatially discrete area of EIN, the precursor of endometrioid carcinoma." (PMID 29604063, 2018). "Polymerase epsilon (POLE), which has recently become the focus for endometrial carcinoma, is a DNA polymerase with a proofreading exonuclease domain." (PMID 29599905, 2018). "The Cancer Genome Atlas (TCGA) defined four distinct endometrial carcinomas prognostic subgroups, POLE ultramutated, microsatellite instability hypermutated (MSI), copy-number-low microsatellite stable (CN-low-MSS), and copy-number-high serous-like (CN-high)." (PMID 30557309, 2018).
endometrial cancer (continued). "In endometrial cancer, MSI-H tumors have an intermediate prognosis, with POLE mutated cancers having the best prognosis and serous-like cancers having the worst." (PMID 29121062, 2017). "In this study, we aimed to validate our previous findings of an enhanced immune response in POLE-mutant and MSI endometrial cancers in a cohort of high-risk patients." (PMID 28344870, 2017). "Somatic mutations of POLE in the exonuclease domain are found in CRC and endometrial cancers that show association with hypermutability." (PMID 28179590, 2017). "In summary, germline and somatic mutations in the POLE and POLD1 genes appear to predispose to, or promote, colorectal and endometrial cancers in part by increasing the rates of SBSs." (PMID 24705290, 2014). "Very interestingly, two additional studies employing next-generation sequencing approaches also very recently reported on the presence of EDMs of POLE in endometroid endometrial carcinomas (EC) at a slightly higher frequency (around 7%) than observed for CRC." (PMID 25124163, 2014). "Molecular profiling has increasing relevance in endometrial cancer, although its clinical utility is most established in early-stage disease, where polymerase ε (POLE)-ultramutated tumours may allow adjuvant de-escalation." (PMID 41574231, 2026). "This cost-effective and efficient SCF primer qPCR system provides an accessible method for routine molecular classification of endometrial cancer in clinical settings, offering a practical alternative to NGS for detecting pathogenic POLE mutations and supporting clinical decision-making." (PMID 41899408, 2026). "These factors stratified endometrial cancer into four subgroups: POLE mut, MMRd, p53abn, and NSMP." (PMID 40431619, 2025). "Although MSI or POLE-mutated status is commonly associated with favorable responses to immunotherapy, some endometrial cancers without these specific alterations have also shown responses." (PMID 40352591, 2025). "Within this framework, our results suggest that POLE-driven endometrial cancers may undergo a comparable form of transcriptional reprogramming, extending from mRNA to the miRNA regulatory layer." (PMID 41226475, 2025). "Determining which molecular subtype (POLE mut, MMRd, p53abn, and NSMP) is a key factor for choosing the appropriate adjuvant therapy.The detection of POLE mut or p53abn subtypes in the early stages of endometrial cancer is now a main criterion for 2023 staging." (PMID 40431619, 2025).